CNTN1 (contactin 1)
Diseases named in the same sentence as CNTN1 in open-access papers (continued):
Sharing a sentence is not in itself a finding about the gene and the disease.
neuroblastoma (1 paper, 2024). Neuroblastoma (NB) is the most common solid, extracranial childhood tumor. "We stratified high- and low-risk neuroblastoma into subtypes based on CNTN1 expression and generated Kaplan–Meier plots for these subtypes using the GSE62564 dataset, and for high-risk neuroblastoma using the TARGET dataset." (PMID 39595172, 2024). "High CNTN1 expression was significantly associated with increased overall survival probability in neuroblastoma patients from both the TARGET and GSE62564 datasets." (PMID 39595172, 2024). "Upregulation of CNTN1 was significantly associated with improved overall survival in both high- and low-risk neuroblastoma patients with the adjusted p-value below 0.1." (PMID 39595172, 2024). "Moreover, high CNTN1 expression is associated with increased overall survival in neuroblastoma patients." (PMID 39595172, 2024). "Importantly, high CNTN1 expression is associated with an increased overall survival probability in neuroblastoma patients." (PMID 39595172, 2024). "In this study, we analyzed publicly available datasets and identified CNTN1 as one of the most significantly overexpressed genes in neuroblastoma tumors." (PMID 39595172, 2024). "Here, we demonstrate that neuroblastoma tumors express significantly higher levels of the neural glycoprotein CNTN1 compared to many other tumor types." (PMID 39595172, 2024). "Our findings provide valuable insight into the role of CNTN1 in neuroblastoma and its potential as a novel therapeutic biomarker." (PMID 39595172, 2024). "Further studies are required to elucidate the mechanisms through which CNTN1 affects tumor growth and progression in neuroblastoma in order to evaluate its potential as a therapeutic target in preclinical and clinical settings." (PMID 39595172, 2024). "To investigate the role of CNTN1 in neuroblastoma, we analyzed several large publicly available datasets of tumor gene expression." (PMID 39595172, 2024). "Analysis of the TARGET database revealed that CNTN1 expression was higher in tumors originating from the thorax compared to those from the adrenal gland, in line with a potential protective role of CNTN1 in neuroblastoma." (PMID 39595172, 2024). "Our findings highlight the potential significance of CNTN1 as a novel biological marker and therapeutic target for neuroblastoma." (PMID 39595172, 2024). "To assess the prognostic role of CNTN1 in neuroblastoma, we analyzed the correlation between patient overall survival (OS) and CNTN1 gene expression using the survminer package in R, with the cutoff point determined by the surv_cutpoint function." (PMID 39595172, 2024). "Our analysis of the Cancer Cell Line Encyclopedia (CCLE) revealed that CNTN1 mRNA expression was highest in neuroblastoma compared to other tumor types, consistent with the known function of CNTN1 as an endogenous neuronal membrane glycoprotein." (PMID 39595172, 2024). "Interestingly, in an orthotopic xenograft mouse model of neuroblastoma, we observed decreased metastasis in mice xenografted with CNTN1 knockout SK-N-AS tumors compared to mice with WT tumors." (PMID 39595172, 2024). "Further investigation of CNTN1 could have significant clinical implications for improving neuroblastoma treatment." (PMID 39595172, 2024). "To investigate the effect of CNTN1 on primary neuroblastoma tumor growth and metastasis in vivo, we established CNTN1 knockout (crCNTN1) using a CRISPR-Cas9 system in both the non-MYCN-amplified SK-N-AS and the MYCN-amplified SK-N-DZ high-risk human neuroblastoma cell lines." (PMID 39595172, 2024). "However, the precise role of CNTN1 in neuroblastoma remains incompletely understood, and its potential as a therapeutic target remains largely unexplored." (PMID 39595172, 2024). "Therefore, we investigated the function of CNTN1 in neuroblastoma, specifically focusing on tumor growth and metastasis in xenograft mouse models." (PMID 39595172, 2024).
neuroblastoma (continued). "Interestingly, when considering MYCN amplification across the entire cohort, high CNTN1 expression was associated with a significantly increased overall survival probability for neuroblastoma patients with non-MYCN-amplified tumors." (PMID 39595172, 2024).
optic neuritis (1 paper, 2018). Optic neuritis is inflammation of the optic nerve, the nerve that carries the visual signal from the eye to the brain.The conditionmay cause sudden, reduced vision in the affected eye(s). "Interestingly, reduction in the expression level of CASPR1/CNTN1 in pre‐clinical optic neuritis/EAE is associated with a concomitant decrease in RIBEYE expression indicating a close functional connection of these proteins in retinal ribbon synapses (Figs 2B2, D2, 3B2, C and 4B2, and EV5)." (PMID 30266776, 2018). "Importantly, the synaptic CASPR1/CNTN1 complex is strongly decreased and the functional synaptic changes occur at an early, pre‐clinical stage of optic neuritis/EAE before the onset of obvious morphological alterations in the optic nerve that subsequently occur at a later time." (PMID 30266776, 2018).
polyradiculoneuropathy (1 paper, 2025). Diseases characterized by injury or dysfunction involving multiple peripheral nerves and nerve roots. "The term autoimmune nodoparanodopathy was first applied to AMAN–AMSAN but later extended to subacute/chronic forms of polyradiculoneuropathy associated with IgG4 antibodies against nodal (neurofascin [NF]-140/186) or paranodal (NF-155, contactin-1/Caspr1) axo-glial proteins." (PMID 39854764, 2025).
retinal degeneration (1 paper, 2021). Degeneration of the retina. "Contactin 1 has a role in regulating synaptic plasticity in the nervous system, so our finding that it was downregulated at P90 in retinal degeneration – a process defined by neural remodelling - was perhaps surprising." (PMID 33811915, 2021).
schizophrenia (1 paper, 2023). A major psychotic disorder characterized by abnormalities in the perception or expression of reality. "In addition, previous studies have shown that changes in the levels of CNTN1, CDH1, and other cell adhesion proteins in peripheral blood are associated with deficit schizophrenia, which may also be related to hypoxia." (PMID 37576864, 2023).
sensory impairment (1 paper, 2020). "Previous studies found that anti-CNTN1 antibodies were associated with either predominant motor or sensory impairment." (PMID 31753915, 2020).
Stroke (1 paper, 2024). Sudden impairment of blood flow to a part of the brain due to occlusion or rupture of an artery to the brain. "Similarly, the relationship between serum levels of contactin-1 (CNTN1), a cellular adhesion molecule involved in axo–glial interaction, and stroke is not well defined, and even the literature is controversial." (PMID 38732018, 2024).
thymoma (1 paper, 2025). A neoplasm arising from the epithelial cells of the thymus. "However, although there was a low number of antibody-tested cases, it was found that CNTN1-IgG was positive in four patients, suggesting autoantibodies might be associated with thymoma-related demyelinating neuropathy." (PMID 40995362, 2025). "It was recently reported that some patients with anti-CNTN1 AN had paraneoplastic status including thymoma." (PMID 40995362, 2025). "In conclusion, we presented detailed clinical information, pathological findings, and biomarker analysis of three patients with anti-CNTN1 AN and concurrent thymoma." (PMID 40995362, 2025). "Thymoma might be a coincidental lesion and the elderly onset in anti-CNTN1 AN compared with anti-NF155 AN might explain the higher comorbidity of neoplasms." (PMID 40995362, 2025). "Here, we describe three patients with anti-CNTN1 AN and concurrent thymoma." (PMID 40995362, 2025). "Clinical features of patients with CNTN1-IgG and concurrent thymoma." (PMID 40995362, 2025). "In this study, we presented three cases of CNTN1-IgG4 and concurrent thymoma in detail." (PMID 40995362, 2025).
tumor (35 papers, 2009 to 2025). "Previous studies have demonstrated that CNTN1 is associated with poor overall survival in many tumor types." (PMID 39595172, 2024). "CNTN1 has also been associated with advanced tumor stage, regional and metastatic disease, and reduced survival in multiple malignancies." (PMID 39595172, 2024). "While patient data suggest that high CNTN1 expression is associated with less aggressive tumor characteristics and increased overall survival, animal studies suggest that CNTN1 knockout suppresses metastasis." (PMID 39595172, 2024). "HCC had higher CNTN-1 mRNA and protein expression than adjacent tissues, which was linked to tumor size and metastasis." (PMID 34659414, 2021). "This association was corroborated by a recent study in which elevated CNTN1 expression was found to positively associate with larger tumor size, advanced tumour stage, higher risk of metastasis and shorter overall survival (OS) in PC patients following radical prostatectomy." (PMID 32752094, 2020). "Thus, future studies should focus on identifying correlated molecular mechanisms to ascertain the association between CNTN1 expression and tumor proliferation." (PMID 33194679, 2020). "CNTN1 physiological expression in the central nerve system and its upregulation in multiple cancer types may qualify it as a tumor-associated antigen (TAA)." (PMID 32752094, 2020). "Our data suggest that potential clinical intervention to reduce tumor phenotypes mediated by the rs55958994-associated enhancer could be to target CNTN1 and/or to use other methods to reduce PCa stem cells." (PMID 31328168, 2019). "CNTN1 has been shown to promote tumor invasion primarily through the regulation of EMT, as well as the regulation of vascular endothelial growth factor (VEGF)." (PMID 39595172, 2024). "Results of immunohistochemistry and Western blot assay showed that CNTN-1 was increased in the xenograft tumor of A549 cells treated with low-dose cisplatin compared with that of controls." (PMID 35711928, 2022). "Contactin 1 promotes tumor invasion and metastasis induced by VEGF-C/Flt-4/Src/p38 MAPK/C/EBPα pathway." (PMID 36518397, 2022). "On the one hand, upregulated Cntn-1 is a marker of poor outcome in tumor diseases; on the other hand, autoantibodies against Cntn-1 are disease-promoting in CIPD." (PMID 34208308, 2021). "In recent years, it has been reported that the abnormal expression of CNTN-1 is closely related to the tumor occurrence and progression." (PMID 33860055, 2021). "Mounting evidence in the past decade have supported CNTN1′s unique role in promoting tumor progression and metastasis in cancers." (PMID 32752094, 2020). "These oncogenic events are resulted via interactions between tumor and stroma, which can be contributed by CNTN1, an adhesion protein." (PMID 32752094, 2020). "The location of CNTN1 gene locus close to a tumor breakpoint provides a potential genetic evidence for CNTN1 to function in tumor formation and progression." (PMID 32752094, 2020). "The expression of CNTN1 was significantly correlated with Flt expression, tumor stage, lymph node metastasis, and patient survival in lung adenocarcinoma patients." (PMID 32752094, 2020). "A review of the literature revealed that CDH17, CNTN-1 and IGF2BP1 were associated with tumor progression and drug resistance and were identified as potential candidates for further analysis." (PMID 31427725, 2019). "And inhibition of CNTN-1 in lung adenocarcinoma has been shown to abolish tumor metastasis and prolong survival in a xenograft model." (PMID 31427725, 2019). "The deletion of the rs55958994-associated enhancer leads to the down-regulation of ITGA5, CDH23, and CNTN1, to defects of tumor initiation, growth, and invasive migration, and to a decrease in the percentage of CSCs." (PMID 31328168, 2019). "Twelve days after tumor implantation, the volumes of CNTN1 transfected xenograft tumors were significantly higher than either untrasfected or empty-vector transfected tumors." (PMID 29673312, 2018).
tumor (continued). "CNTN1 (contactin 1), a neural cell adhesion protein, was preferentially expressed in PCSCs and promoted tumor regeneration, invasion, progression and metastasis, via AKT activation and reduced E-cadherin." (PMID 29152153, 2017). "Knockdown of CNTN-1 resulted in extensive inhibition of tumor metastasis and improvement of survival in an animal model." (PMID 23606831, 2013). "Suppression of CNTN-1 expression abolishes the ability of tumor cells to invade Matrigel in vitro as well as the polymerization of filamentous-actin and the formation of focal adhesion structures." (PMID 23606831, 2013). "Recent evidence suggests that the gene for CNTN-1 plays an essential role in tumor invasion and metastasis." (PMID 23606831, 2013). "Contactin- 1 is a metastasis promoter gene that plays anessential role in tumor metastasis and tumor invasion." (PMID 21079744, 2010). "Down-regulation was seen for CNTN1, CXCL13, MAOB, PAGE4, PENK, SPOCK3 in CP compared to NP as well as for HSD17B2, SALL1, TRPA1 for tumor-associated bladder stromal cells compared to normal bladder." (PMID 19737398, 2009). "In vivo studies were performed to elucidate the role of contactin-1 (CNTN1) in tumor progression." (PMID 39595172, 2024). "Contactin-1 (CNTN1) is a neuronal adhesion protein involved in tumor progression." (PMID 38730433, 2024). "Furthermore, a previous study on tumor cells suggested that CNTN1 affects the cell cycle and cell growth, potentially influencing the trait under investigation." (PMID 37372438, 2023). "To sum up, we speculate that MMP8, MMP11, TFDP3, F2, and CNTN1 can promote the progression of GAC while MYB could be a tumor suppressor in GAC." (PMID 32309437, 2020). "This shows that CNTN1 is broadly involved in several regulatory networks for tumor progression." (PMID 33194679, 2020). "This upregulation of CNTN1 was positively correlated with tumor size, TNM and tumor stage." (PMID 32752094, 2020). "It has also been demonstrated that silencing CNTN-1 renders resistant cells more sensitive to a chemotherapeutic drug than parent cells, and enhances the apoptosis induced by cisplatin, leading to inhibition of tumor invasion and metastasis in lung cancer." (PMID 31427725, 2019). "It is evident that CNTN-1 plays an essential role in tumor invasion and metastasis and may be a promising therapeutic target in cancer therapy." (PMID 31427725, 2019). "Moreover, silencing of CNTN1 inhibits tumor metastasis and increased tumor survival in a metastatic murine tumor model." (PMID 29673312, 2018). "The gene for CNTN-1 was found to play an essential role in tumor invasion and metastasis." (PMID 23606831, 2013). "Moreover, CNTN1 expression varies with tumor grade and primary tumor site, with higher expression observed in less aggressive grade 1 tumors, as well as tumors originating from the thorax, a clinically favorable primary site, compared to those in the adrenal gland." (PMID 39595172, 2024). "Interestingly, in a study exploring the therapeutic efficacy of Ganoderma lucidum extract (GLE), a potentially effective tumor growth inhibitor, CNTN1 was identified to be a part of the hub mRNA down-expressed in GLE-treated Hepa1–6-bearing C57BL/6 mice, mediated by miRNA mmu-miR23a-5p." (PMID 32752094, 2020). "Upregulation of JAG1 is accompanied by increased Notch and CNTN1 expression indicating that the tumor cells themselves were, at least in part, target of the increased Jagged 1 signaling as there obviously were interactions between tumor cells via Jagged 1 / Notch." (PMID 29432466, 2018). "Moreover, CNTN1 expression also enhanced tumor growth in nude mice." (PMID 29673312, 2018). "CNTN1 also serves as a functional ligand of Notch1 and promotes Notch1 activation by releasing the Notch intracellular domain (NCID), thereby promoting tumor progression." (PMID 38562021, 2024).
tumor (continued). "It was thus possible to identify genes (CNTN1, FAT3, EPHA3, EPHA5, NLGN1, etc.)that contribute to PC2 and are differentially expressed in radial glial cells between normal and tumor samples." (PMID 38609519, 2024). "The findings also showed that the mRNA expression of CNTN1, ENO1, and MAGEA1 were higher in tumor tissues, whereas the mRNA expression of GATA3 was higher in normal tissues." (PMID 35846128, 2022). "The qRT-PCR results demonstrated that expression of CNTN1, ENO1, and MAGEA1 were higher in tumor tissues, whereas the expression of GATA3 was higher in normal tissues." (PMID 35846128, 2022). "Compared with adjacent normal tissue, the expression of CNTN-1 in HCC tumors has been reported to be much higher, with CNTN-1 level positively correlated with tumor size, status of metastasis and TNM (tumor, node, metastasis) stage." (PMID 31427725, 2019). "During our analysis the most prominent differences connected with the location of the tumor were noted for the IRX2, PAX3, CXCL14, LHX2, SIX6, CNTN1 and SIX1 genes." (PMID 26497896, 2015). "This hypothesis was supported by our snRNA-seq analysis, in which we clearly observed that genes related to neuronal migration and axon guidance (CNTN1, PTPRG, NTRK2, FAT3, etc.)were more upregulated in neuron cell clusters than in tumor cell clusters." (PMID 38609519, 2024). "The significantly regulated genes identified in both KYSE150 and KYSE410 cells were found to be involved in cell adhesion (PCDH family genes, CLDN1, CNTN1), cell apoptosis (MAPK10/JNK3, PYCARD), tumor suppression (TUSC3, SAMD9L) and immunity regulation (IFNL3)." (PMID 32089740, 2020). "This suggests that CNTN1 is essential for tumor metastasis, but not tumor formation and proliferation." (PMID 33194679, 2020). "Also, we identified NCAM1, CNTN1, SCG2, CADM1, IL-8, NPTX1, and APOD as PSCB in the tumor secretome." (PMID 31455042, 2019). "Different expression level of CNTN-1 protein was detected in tumour samples and in noncancerous gastric samples." (PMID 23606831, 2013). "Different expression level of CNTN-1 mRNA was detected in tumour samples and in noncancerous gastric samples." (PMID 23606831, 2013). "In addition to its regulatory role in the nervous system, CNTN1 functions as a glycosylphosphatidylinositol anchor neural cell adhesion molecule (NCAM), which is involved in tumor cell adhesion, invasion and metastasis." (PMID 22580838, 2012). "Additionally, the location of CNTN1 in the 12q11-q12 chromosomal region, which is a breakpoint region in several types of cancer, suggests that CNCT1 is involved in tumor formation or progression." (PMID 22580838, 2012). "As a result, we observed that neuron-related genes (CNTN1, FAT3, PTPRG, NTRK2, etc.)annotated to categories such as nervous system development, neuron differentiation, generation of neurons, and neurogenesis were downregulated in tumor cluster cells (Online Resource)." (PMID 38609519, 2024). "Tumor samples expressed higher level of CNTN-1 mRNA than that in noncancerous gastric samples." (PMID 23606831, 2013). "Tumor samples expressed higher level of CNTN-1 protein than that in noncancerous gastric samples." (PMID 23606831, 2013).